CFAP141 (cilia and flagella associated protein 141)
Description:
Microtubule inner protein (MIP) part of the dynein-decorated doublet microtubules (DMTs) in cilia axoneme, which is required for motile cilia beating.
Synonyms: C1orf189
Tractability: Small molecule: a structure with a bound ligand is known.
Gene: Protein-coding gene on chromosome 1 (154,199,085 to 154,206,333, reverse strand). Ensembl gene ENSG00000163263.
Subcellular location: Cytoplasm, cytoskeleton, cilium axoneme; Cytoplasm, cytoskeleton, flagellum axoneme
Gene Ontology:
Molecular function: protein binding
Biological process: flagellated sperm motility
Cellular component: axonemal microtubule; axonemal A tubule inner sheath; sperm flagellum; axoneme
Genetic constraint (gnomAD): Loss-of-function variants: 14 observed, 16.83 expected, observed/expected ratio (o/e) 0.83, 90% interval 0.55 to 1.3. The upper end of that interval is the gene's LOEUF score, 1.3, which puts it in group 5 of 6, group 1 being the genes least tolerant of losing a copy. Missense variants: 95 observed, 106.32 expected, observed/expected ratio (o/e) 0.89, 90% interval 0.76 to 1.06. Synonymous variants: 42 observed, 36.03 expected, observed/expected ratio (o/e) 1.17, 90% interval 0.91 to 1.51.
Homologues: Orthologues: chimpanzee CFAP141 (99% identical), pig CFAP141 (86% identical), guinea pig CFAP141 (80% identical), rat Cfap141 (78% identical), mouse Cfap141 (74% identical).